ANXA2 (annexin A2)
Description:
Calcium-regulated membrane-binding protein whose affinity for calcium is greatly enhanced by anionic phospholipids. It binds two calcium ions with high affinity. May be involved in heat-stress response. Binds to endosomes damaged by phagocytosis of particulate wear debris and participates in endosomal membrane stabilization, thereby limiting NLRP3 inflammasome activation (By similarity). Required for endothelial cell surface plasmin generation and may support fibrinolytic surveillance and neoangiogenesis (By similarity). (Microbial infection) Binds M.pneumoniae CARDS toxin, probably serves as one receptor for this pathogen. When ANXA2 is down-regulated by siRNA, less toxin binds to human cells and less vacuolization (a symptom of M.pneumoniae infection) is seen.
Synonyms: PAP-IV; ANX2; ANX2L4; CAL1H; LPC2D; LIP2; HEL-S-270; LPC2; P36
Tractability: Small molecule: a structure with a bound ligand is known; it has a high-quality binding pocket. Antibody: UniProt places it where antibodies can reach, with high confidence; its Gene Ontology location is reachable by antibodies, with high confidence; the Human Protein Atlas places it where antibodies can reach. PROTAC: UniProt records ubiquitination sites on it; ubiquitination databases record sites on it; its protein half-life has been measured; a small molecule that binds it is known.
Target class: Ion channel; Annexin; Other ion channel
Gene: Protein-coding gene on chromosome 15 (60,347,134 to 60,402,883, reverse strand). Ensembl gene ENSG00000182718.
Subcellular location: Secreted, extracellular space, extracellular matrix, basement membrane; Melanosome
Subcellular location (Human Protein Atlas): Plasma membrane; Cytosol; Predicted to be secreted
Pathways (Reactome):
Immune System: Gene and protein expression by JAK-STAT signaling after Interleukin-12 stimulation; Neutrophil degranulation
Cellular responses to stimuli: Turbulent (oscillatory, disturbed) flow shear stress activates signaling by PIEZO1 and integrins in endothelial cells
Developmental Biology: Developmental Lineage of Pancreatic Ductal Cells
Hemostasis: Dissolution of Fibrin Clot
Muscle contraction: Smooth Muscle Contraction
Gene Ontology:
Molecular function: cadherin binding involved in cell-cell adhesion; calcium-dependent phospholipid binding; calcium-dependent protein binding; identical protein binding; phosphatidylinositol-4,5-bisphosphate binding; phospholipase A2 inhibitor activity; protease binding; protein binding; RNA binding; S100 protein binding; serine-type endopeptidase inhibitor activity; phosphatidylserine binding; AP-3 adaptor complex binding; calcium ion binding; cytoskeletal protein binding; phospholipase inhibitor activity
Biological process: angiogenesis; membrane raft assembly; negative regulation of low-density lipoprotein particle receptor catabolic process; negative regulation of receptor internalization; osteoclast development; positive regulation of low-density lipoprotein particle clearance; positive regulation of plasminogen activation; positive regulation of receptor recycling; positive regulation of receptor-mediated endocytosis involved in cholesterol transport; positive regulation of vacuole organization; positive regulation of vesicle fusion; vesicle budding from membrane; cell adhesion; positive regulation of exocytosis; positive regulation of plasma membrane repair; cell-cell adhesion; mRNA transcription by RNA polymerase II; negative regulation of transport; positive regulation of transcription by RNA polymerase II; regulation of neurogenesis
Cellular component: adherens junction; AnxA2-p11 complex; cell surface; cytoplasm; endosome; extracellular exosome; extracellular matrix; extracellular region; late endosome membrane; lipid droplet; lysosomal membrane; membrane; membrane raft; midbody; nucleus; PCSK9-AnxA2 complex; plasma membrane; plasma membrane protein complex; RNA polymerase II transcription regulator complex; vesicle; azurophil granule lumen; basolateral plasma membrane; cytosol; nuclear matrix; vesicle membrane; and 7 more
Genetic constraint (gnomAD): Loss-of-function variants: 23 observed, 33.07 expected, observed/expected ratio (o/e) 0.7, 90% interval 0.5 to 0.99. The upper end of that interval is the gene's LOEUF score, 0.99, which puts it in group 4 of 6, group 1 being the genes least tolerant of losing a copy. Missense variants: 312 observed, 340.2 expected, observed/expected ratio (o/e) 0.92, 90% interval 0.83 to 1.01. Synonymous variants: 138 observed, 127.15 expected, observed/expected ratio (o/e) 1.09, 90% interval 0.94 to 1.25.
Homologues: Orthologues: chimpanzee ANXA2 (100% identical), macaque ANXA2 (100% identical), pig ANXA2 (98% identical), mouse Anxa2 (98% identical), guinea pig ANXA2 (97% identical), rat Anxa2 (97% identical), dog ANXA2 (86% identical), rat AABR07018244.2 (84% identical), tropical clawed frog anxa2 (81% identical), zebrafish anxa2a (67% identical), zebrafish anxa2b (65% identical), Drosophila melanogaster AnxB9 (39% identical), and 1 more. Paralogues in human: ANXA1 (52% identical), ANXA11 (46% identical), ANXA4 (46% identical), ANXA6 (46% identical), ANXA3 (45% identical), ANXA8 (43% identical), ANXA8L1 (43% identical), ANXA5 (42% identical), ANXA7 (42% identical), ANXA9 (40% identical), ANXA13 (40% identical), ANXA10 (37% identical).
Diseases named in the same sentence as ANXA2 in open-access papers:
ANXA2 is named in the same sentence as 348 diseases in open-access papers, as found by Europe PMC text mining. Sharing a sentence is not in itself a finding about the gene and the disease. The quoted sentences say what the papers report.
breast carcinoma (148 papers, 2008 to 2025). "Ultimately, we found that knockdown of ANXA2 in breast cancer-associated fibroblasts not only affected the expression of SPOCK1 but also led to a decrease in IGF1 expression." (PMID 40837013, 2025). "For example, in the MCF10A isogenic breast cancer progression model, ANXA2 levels in EVs are highly associated with breast cancer cells’ aggressiveness." (PMID 36835116, 2023). "In in vivo Matrigel plug assays, EVs secreted from TNBC cells were shown to promote angiogenesis through Annexin A2, and this was associated with the worsening of clinical pathological characteristics in breast cancer patients." (PMID 38111675, 2023). "This approach identified an interesting molecule, annexin A2, which is firmly associated with cancer metastatic progression in a plethora of cancer types including breast cancers." (PMID 37091157, 2023). "EGFR alone cannot drive the progression of metastatic PCa tumours, but its linked to its upstream fibrinolytic receptor ANXA2, are together known to the PCa and breast cancer progression." (PMID 36224238, 2022). "Aberrant ANXA2 expression is associated with various malignancies, including colorectal cancer, pancreatic cancer, breast cancer, and EC." (PMID 35805203, 2022). "Nuclear translocation of ANXA2 also exhibited a protective effect against DNA damage caused by irradiation in human lung and breast cancer cells." (PMID 36247003, 2022). "A unique conjugate of curcumin was reported with membrane associated protein, Annexin A2 for the treatment of xenograft model of highly invasive Breast cancer cell line MCF10CA1a, which also showed overexpression of Annexin A2." (PMID 35582033, 2021). "In order to tell the activity of Anxa2 in NF-κB associated EMT in breast cancer, we first assessed the interaction of Anxa2 with NF-κB p50 subunit in breast cancer MDA-MB-231 and MCF-7 cells by coIP analysis." (PMID 32244350, 2020). "Taken together, our results suggest that high serum AnxA2 levels in breast cancer patients is associated with poor prognosis." (PMID 33374917, 2020). "Our previous study indicates a strong association of AnxA2 expression with AA women with breast cancer and implicating AnxA2 as a contributor to the aggressive biology of TNBC." (PMID 31992335, 2020). "Our analyses on breast cancer cell lines demonstrated that secretion of AnxA2 is associated with its tyrosine 23 (Tyr23) phosphorylation in cells." (PMID 33374917, 2020). "The expression of serum exo-AnxA2 and its association with clinicopathological features of the breast cancer patients were determined." (PMID 31992335, 2020). "The high expression of serum AnxA2 in breast cancer was associated with tumor grade and poor survival." (PMID 33374917, 2020). "This study is innovative as it established the high diagnostic role of serum AnxA2 in the most aggressive subtype of breast cancer patients, TNBC." (PMID 33374917, 2020). "This agrees with our observations of Annexin A2 suppression diminishing the migratory capacity of breast cancer cells and potentially correlating with loss of EMT marker, E-Cadherin, in specific cases." (PMID 32629869, 2020). "The high expression of exo-AnxA2 was associated with tumor grade, poor overall survival, and disease-free survival of breast cancer patients." (PMID 31992335, 2020). "Overall, this study highlights the diagnostic and prognostic significance of AnxA2 in breast cancer." (PMID 33374917, 2020). "The clinicopathological features such as tumor size, grade, lymph node metastasis, and TNM stage and its association with serum exo-AnxA2 relative expression status were examined in breast cancer patients." (PMID 31992335, 2020). "Together, these findings suggest that high levels of AnxA2 detected in serum samples of breast cancer patients is significantly associated with high tumor grades." (PMID 33374917, 2020). "The high expression of serum AnxA2 was significantly associated with tumor grades and poor survival of the breast cancer patients." (PMID 33374917, 2020).
breast carcinoma (continued). "In this work, we further explored the effect of Rack1 on the invasive and metastatic potential in drug-resistant breast cancer cells, and investigated the mechanism underlying the regulation of Anxa2 Tyr23 phosphorylation." (PMID 31113450, 2019). "The interaction between Anxa2 and Rack1/Src is responsible for the association between drug resistance and invasive/metastatic potential in breast cancer cells." (PMID 31113450, 2019). "In this study, we found that LncCCAT1 was mainly localized in the cytoplasm and that endogenous miR-204/211, miR-148a/152, and ANXA2 protein were associated with LncCCAT1 in breast cancer cells." (PMID 31695775, 2019). "Our findings suggest that the interaction between Anxa2 and Rack1/Src is responsible for the association between drug resistance and aggressive behavior in breast cancer cells." (PMID 31113450, 2019). "We observed that the reduction of phosphorylated Anxa2 was associated with decreased invasiveness in MDR breast cancer cells." (PMID 31113450, 2019). "Evidence has shown AnxA1, AnxA2, AnxA8 are associated with the basal-like phenotype and potentiates poor prognosis of basal-like breast cancer." (PMID 29416802, 2018). "We observed a significant low expression of E-cadherin in the Anxa2 high expression group (P = 0.0001), supporting a functional association between Anxa2 overexpression and breast cancer EMT development." (PMID 26307676, 2015). "A multifunctional protein, AnxA2 is involved in various cellular activities and its dysregulation is implicated in multiple diseases including breast cancer." (PMID 26272794, 2015). "Studies have found that high expression of ANXA2 is associated with the invasive behavior of breast cancer and serves as an important indicator of poor prognosis in triple-negative breast cancer35knockdown of ANXA2 inhibited cell migration and invasion ability." (PMID 40481236, 2025). "Based on these findings, we hypothesized that ANXA2 might act as an upstream regulator of SPOCK1 in breast cancer-associated fibroblasts (CAFs)." (PMID 40837013, 2025). "Interestingly, serum exosomal-annexin A2 (exo-AnxA2) has been linked to angiogenesis and metastasis in breast cancer." (PMID 38794316, 2024). "High expression of exo-AnxA2 levels in breast cancer was significantly associated with tumor grade (P < 0.0001), poor overall survival (hazard ratio (HR) 2.802; 95% confidence intervals (CI) = 1.030–7.620; P = 0.0353), and poor disease-free survival (HR 7.934; 95% CI = 1.778–35.398; P = 0.0301)." (PMID 31992335, 2020). "In addition, Kaplan–Meier curves revealed that high expression of serum AnxA2 was significantly associated with poor overall survival and poor diseases-free survival of the breast cancer patients." (PMID 33374917, 2020). "The diagnostic value of breast cancer showed that the expression of exo-AnxA2 levels in serum could distinguish the breast cancer patients (AUC value 0.9484 ± 0.01327) from the non-cancer females." (PMID 31992335, 2020). "In addition, the significant association between the serum AnxA2 levels and tumor grades were also observed in breast cancer patients." (PMID 33374917, 2020). "In addition, the association of exo-AnxA2 expression with tumor grade of breast cancer patients is specifically associated with the triple-negative subtypes of breast cancer." (PMID 31992335, 2020). "Altered calcium homeostasis has been observed within breast cancer, however, it is currently unclear whether the dysregulation of calcium binding proteins like Annexin A2 are a cause or a consequence of this imbalance." (PMID 32629869, 2020). "Furthermore, we observed that the diagnostic value of serum AnxA2 was significantly high in TNBC compared with other breast cancer subtypes." (PMID 33374917, 2020). "Additionally, the Src/ANXA2/STAT3 pathway has been implicated in breast cancer invasion and metastasis formation." (PMID 30050103, 2018).
breast carcinoma (continued). "The proliferative activity of Anxa2 has been associated with tumour progression, since increased Anxa2 expression correlates with a more invasive phenotype and induces proliferation and invasion signalling in human breast cancer cells." (PMID 28178326, 2017). "A recent study indicated that ubiquitination could cause ANXA2 overexpression in breast cancer tissue compared to normal tissue." (PMID 24591759, 2014). "Furthermore, our evidence of a link between collagen abundance and the activation of this pro-metastatic modification of Annexin A2 goes some way to explaining our previous findings of Annexin A2’s integral role in breast cancer metastasis and the associated ECM dysregulation seen in the disease." (PMID 37941562, 2023). "A growing body of evidence shows that the dysregulation of ANXA2 expression is associated with tumorigenesis and immunity in a variety of cancers, such as glioma, oral squamous cell carcinoma, pancreatic cancer, colorectal cancer, breast cancer, thyroid cancer, and gastric cancer." (PMID 36425071, 2022). "Consistent with studies reported previously in other cancers, the results of the present study further confirmed that the circulating concentrations of AnxA2 in serum could be used as a diagnostic and prognostic serological biomarker for breast cancer patients." (PMID 33374917, 2020). "In breast cancer patients, ANXA2 expression is markedly elevated in tumour tissues and serum compared to normal controls, with the most pronounced upregulation observed in TNBC subtypes." (PMID 40234383, 2025). "Subsequently, we compared the expression levels of SPOCK1 and IGF-1 between parental breast cancer fibroblasts and ANXA2-knockdown breast cancer fibroblasts." (PMID 40837013, 2025). "We found that the expression of both SPOCK1 and IGF-1 was reduced in ANXA2-knockdown breast cancer fibroblasts." (PMID 40837013, 2025). "It was reported that ANXA2 interacts with the heat shock protein 27 (HSP27) mediating in UVC-resistance in AP1 breast cancer cells." (PMID 39562436, 2025). "In breast cancer CAF cell lines with knockdown of ANXA2 we found that the expression of both SPOCK1 and IGF1 was reduced." (PMID 40837013, 2025). "By activating the PI3 K/AKT pathway, ANXA2 enhanced the migration and invasion capability of breast cancer cells." (PMID 40481236, 2025). "ANXA2 has been identified as a potential prognostic biomarker in many cancers such as breast cancer and HCC." (PMID 38658569, 2024). "Studies on breast cancer have shown that ANXA2 expression is strongly correlated with epidermal growth factor (EGFR) expression and the EMT." (PMID 39057791, 2024). "Previous studies suggested that the ANXA2 expression was higher in breast cancer than corresponding normal tissues." (PMID 36713082, 2023). "Among the 110 low-cytoplasmic-AQP1-expressing samples, 21.8% (24/110) of breast cancer tissues showed positive ANXA2 membranous expression." (PMID 36803413, 2023). "LOXL4 has a new role in breast cancer progression that occurs via an interaction with annexin A2 and integrin β-1 on the cell surface." (PMID 37091157, 2023). "For example, using anti-Anxa2 antibodies to treat human breast cancer cells proved effective in preventing cancer development." (PMID 37955107, 2023). "ANXA2 has been found to be upregulated in many malignant tumors, including colorectal cancer, breast cancer, renal cell carcinoma, colorectal cancer, hepatocellular carcinoma and neuroblastoma." (PMID 36916296, 2023). "ANXA2 was expected to provide a relevant target, since it promotes cancer progression in various cancer types, including breast cancer, pancreatic cancer, or glioblastoma." (PMID 38092984, 2023). "In breast cancer, increased levels of p-ANXA2 (Tyr 24) in the cytoplasm promote cancer cell proliferation." (PMID 38141769, 2023). "Using immunoblot analysis we firstly investigated how the expression and regulation of Annexin A2 in breast cancer cells is affected by the presence of collagen-I." (PMID 37941562, 2023).